ENSG00000278421
Gene: Miscellaneous RNA gene on chromosome X (74,274,341 to 74,274,411, forward strand). Ensembl gene ENSG00000278421.
Gene Ontology:
Biological process: positive regulation of gene expression